LINC01480 (long independently transcribed non-coding RNA 1480)
Gene: Long non-coding RNA gene on chromosome 19 (41,530,801 to 41,540,899, forward strand). Ensembl gene ENSG00000270164.
Diseases named in the same sentence as LINC01480 in open-access papers:
LINC01480 is named in the same sentence as 3 diseases in open-access papers, as found by Europe PMC text mining. Sharing a sentence is not in itself a finding about the gene and the disease. The quoted sentences say what the papers report.
endometrial cancer (2 papers, 2019 to 2022). Primary or metastatic malignant neoplasm involving the endometrium (mucous membrane that lines the endometrial cavity). "Chen and colleagues showed that LINC00958 was overexpressed in endometrial cancer, and LINC01480 was shown to be required to express the micropeptide." (PMID 31804973, 2019).
lung adenocarcinoma (1 paper, 2022). A carcinoma that arises from the lung and is characterized by the presence of malignant glandular epithelial cells. "Compared with normal lung-epithelial cells (BEAS-2B), the expression level of LINC01415, FRMD6-AS1 and FAM83A-AS1 was significantly higher in lung adenocarcinoma cells (A549/PC9), while the expression level of MED4-AS1 and LINC01480 was lower in lung adenocarcinoma cells." (PMID 36186456, 2022).
LINC01480 also shares sentences with these, for which no sentence is quoted: cervical cancer (1 paper).